RRM2 (ribonucleotide reductase regulatory subunit M2)
Diseases named in the same sentence as RRM2 in open-access papers (continued):
Sharing a sentence is not in itself a finding about the gene and the disease.
prostate carcinoma (continued). "Our functional studies provide direct evidence that CUDC‐907 induces DNA damage and apoptosis in prostate cancer cells at least partially through down‐regulation of CHK1, Wee1, RRM1 and RRM2." (PMID 32459381, 2020). "Remarkably, hsa-miR-193 in prostate cancer was shown to target FOXM1 and RRM2, the last being one of the genes composing the prognostic 10-gene signature." (PMID 33333738, 2020). "To substantiate the hypothesis that RRM2 influences ANXA1 content in PCa cells, we meticulously examined the protein and mRNA levels of ANXA1 following RRM2 knockdown in prostate cancer cells." (PMID 37968699, 2023). "Targeting RRM2, ANXA1, or the PI3K/AKT pathway may offer promising therapeutic strategies to overcome docetaxel resistance in prostate cancer." (PMID 37968699, 2023). "Addressing these limitations through future research endeavours will improve the understanding of the role of RRM2, ANXA1, and the PI3K/AKT pathway in therapeutic resistance in prostate cancer and facilitate the development of more effective treatment strategies." (PMID 37968699, 2023). "Furthermore, we scrutinized patients experiencing biochemical recurrence of prostate cancer (GSE120741) and identified notably heightened RRM2 expression in these cases." (PMID 37968699, 2023). "In addition, We assessed the impact of RRM2 knockdown, ANXA1 over-expression, and PI3K/AKT pathway inhibition on the sensitivity of prostate cancer cells to docetaxel." (PMID 37968699, 2023). "The results demonstrate that the EGR1 exhibited the highest mutation frequency followed by RRM2 and TPP1, while both SOCS2 and C11or54 do not show any mutations in prostate cancer samples." (PMID 35812443, 2022). "In addition, high RRM2 expression has also been demonstrated to promote epithelial-mesenchymal transition (EMT) and angiogenesis in prostate cancer, resulting in poor patient outcomes." (PMID 36428626, 2022). "Finally, three pathway genes (GSTP1, GSTM5, RRM2) with non-zero coefficients were obtained for constructing the prostate cancer prediction model." (PMID 40426879, 2025). "A relevant study on prostate cancer, which had integrated data from cell lines and clinical cohorts, revealed that COH29 inhibited oncogenic activity in vitro and could be a potential therapeutic option for this type of cancer, since RRM2 upregulation was related with poorer outcome." (PMID 34439352, 2021). "However, the role of RRM2 in prostate cancer has not been established yet." (PMID 30286759, 2018).
liver cancer (44 papers, 2016 to 2025). An epithelial or non-epithelial malignant neoplasm that arises from the liver. "Consistent with our study, elevated levels of RRM2 have been linked to unfavorable outcomes in multiple types of malignancies including liver cancer, pancreatic tumors and stomach cancer 46-48." (PMID 40303288, 2025). "The high expression of RRM1 and RRM2 is associated with a worse prognosis in patients with liver cancer." (PMID 36713030, 2023). "In the same cohort, the discriminative ability of liver cancer for AFP was 0.502 (95% CI: 0.418-0.586), indicating that RRM1 and RRM2 had great potential to be diagnostic biomarkers for liver cancer." (PMID 36713030, 2023). "Serum RRM2 is valuable as a biomarker for assessing the extent to which ferroptosis is suppressed, thereby improving the diagnostic efficiency of liver cancer." (PMID 36553600, 2022). "Serum RRM2 will be useful as a biomarker to evaluate the degree to which ferroptosis is suppressed and improve diagnostic efficiency for liver cancer." (PMID 33372599, 2020). "The area under the receiver operating characteristic curve (AUC-ROC) analysis indicated that serum RRM2 (AUC: 0.863, 95% CI 0.821–0.904) was a better diagnostic marker of liver cancer than AFP (AUC: 0.798, 95% CI 0.745–0.851)." (PMID 33372599, 2020). "We also preliminarily verified that serum RRM2 is a potential diagnostic biomarker for liver cancer." (PMID 33372599, 2020). "Additionally, CCK-8, Edu and RT-PCR assays were used to validate that RRM2 acts as an oncogene in liver cancer cells and its association with HBx." (PMID 36518297, 2022). "In addition, higher serum RRM2 concentrations were significantly associated with higher tumor stage in liver cancer." (PMID 33372599, 2020). "The overexpression of RRM2 is linked with tumor progression in liver cancer." (PMID 33372599, 2020). "The potential diagnostic value of serum RRM2 to predict liver cancer was also evaluated." (PMID 33372599, 2020). "Additionally, the association between elevated RRM2 serum levels and advanced tumor stage in liver cancer suggests that it could serve as a promising indicator of sensitivity to ferroptosis and as a factor that can be targeted for cancer therapy." (PMID 38738178, 2024). "However, serum RRM2 was elevated only in the patients with liver cancer among the cancer types we tested, which might be due to the mechanisms underlying how RRM2 release into the blood stream varies among different types of cancers." (PMID 33372599, 2020). "Assays such as RAP-MS have revealed the role of lincNMR and its interaction with YBX1 and RRM2, leading to liver cancer." (PMID 40861865, 2025). "Extensive research has explored the importance of RRM2 and its impact on liver cancer, as well as other cancer types by the regulation and modification of proteins, making it a vital component for tumor progression and a potential biomarker for certain cancer." (PMID 39118438, 2024). "To determine the involvement of RRM2 and RRM2B in HB cell drug response, we treated tdT, RRM2OE and RRM2BOE HepG2 cells with six common liver cancer drugs and the two RRM2 inhibitors triapine and MK1775." (PMID 36882565, 2023). "High expression of RRM2, MADAL1, MELK, NCAPG and ASPM were associated with poor OS for liver cancer patients." (PMID 35928445, 2022). "Taken together, our results suggest TOP2A, RRM2, NEK2, CDK1, and CCNB1 as HCC-associated hub genes that can serve as potential prognostic biomarkers in liver cancer." (PMID 34681056, 2021). "In previous studies, it has been demonstrated that inhibition of RRM2 significantly inhibits the proliferation of liver cancer cells." (PMID 34539726, 2021). "RRM2 suppresses ferroptosis in liver cancer cells by promoting GSH synthesis and maintaining GPXS activity." (PMID 34499810, 2021). "In liver cancer, researchers found that RRM2 was capable of sustaining intracellular GSH by protecting GSS from degradation." (PMID 34386492, 2021).
liver cancer (continued). "Inhibition of aurora kinase A (AURKA) can suppress ferroptosis in upper gastrointestinal cancers, and RRM2 protects against ferroptosis in liver cancer." (PMID 34395526, 2021). "Taken together, our results strongly indicated that liver cancer patients with an upregulated level of TOP2A, RRM2, NEK2, CDK1, and CCNB1 were associated with poor prognosis." (PMID 34681056, 2021). "In this study, we further clarified that high expression of RRM2 is another potential intracellular anti-ferroptotic event in liver cancer." (PMID 33372599, 2020). "RRM2 showed specifically elevated levels in liver cancer and inhibited ferroptosis by stimulating GSH synthesis via GSS." (PMID 33372599, 2020). "RRM2 was also elevated in a series of tumor tissues compared to normal tissues from their corresponding organs, suggesting that similar to liver cancer, RRM2 exerts anti-ferroptotic activities in other cancers." (PMID 33372599, 2020). "In conclusion, we elucidated that RRM2 exerts anti-ferroptotic function in liver cancer cells by sustaining intracellular GSH by protecting GSS from degradation." (PMID 33372599, 2020). "LincNMR and YBX1 mRNA expression significantly correlate in liver cancer patient samples as well as with RRM2, TK1, and TYMS mRNA expression." (PMID 32587247, 2020). "Of note, we provided further evidence that serum RRM2 is a promising biomarker for the diagnosis of liver cancer." (PMID 33372599, 2020). "To investigate the impact of RRM2 downregulation on restoring normal cellular functions and reversing liver cancer characteristics, we assessed the viability and clonogenic potential of HepG2 cells after transfection via MTT and colony formation assays, respectively." (PMID 40493217, 2025). "IHC analysis via the HPA revealed moderate to high RRM2 staining in 20% of liver cancer samples, which is the highest percentage among other cancer types, whereas RRM2 protein expression was undetectable in normal hepatocytes, suggesting that RRM2 is also active at the proteomic level in HCC." (PMID 40493217, 2025). "RAP-MS in liver cancer revealed lincNMR-YBX1/RRM2 interactions driving cancer mechanisms." (PMID 40861865, 2025). "Some scientists have also reported that the application of the antitumor drug didox, a derivative of hydroxyurea, can target RRM2 and inhibit its activity by quenching tyrosine free radicals at the enzyme active site, thereby suppressing the proliferation of liver cancer cells." (PMID 40510157, 2025). "In addition, a study has also shown that RRM2 acted as an anti-ferroptotic role through sustaining GSH synthesis in liver cancer." (PMID 40303288, 2025). "RRM2 protected against ferroptosis and worked as a tumor biomarker in liver cancer." (PMID 38820515, 2024). "Importantly, we demonstrated that RRM1 and RRM2 were not only highly expressed in liver cancer patients but also multiple liver cancer cell lines, consistent with previous studies." (PMID 36713030, 2023). "Correlation analysis also indicated that RRM1 and RRM2 had the highest correlation in liver cancer." (PMID 36713030, 2023). "To demonstrate the oncogene function of RRM2, we conducted experiments with liver cancer cells." (PMID 36518297, 2022). "In liver cancer, RRM2 can inhibit hypertrophy by stimulating GSS to synthesize GSH." (PMID 35898471, 2022). "RRM2, a regulator of DNA replication and repair, could protect liver cancer cells against ferroptosis." (PMID 34276794, 2021). "RRM2 exerts an anti-ferroptotic role in liver cancer cells by sustaining GSH synthesis." (PMID 33372599, 2020). "Furthermore, the effects of RRM2 on elevating GSH were abolished when GSS was knocked out by CRISPR-Cas9 technology in both HepG2 and SMMC-7721 cells, demonstrating that GSS is a prerequisite for RRM2 to upregulate GSH in liver cancer cells." (PMID 33372599, 2020).
liver cancer (continued). "Because RRM2 has roles in protecting liver cancer cells against ferroptosis, testing serum RRM2 might also be a promising method to predict ferroptosis resistance for ferroptosis-based treatments for liver cancer." (PMID 33372599, 2020). "We discovered that RRM2 exhibits protumorigenic activity in liver cancer." (PMID 33372599, 2020). "Since RRM2 was specifically elevated in serum from liver cancer patients, we investigated whether serum RRM2 can be used as a diagnostic biomarker for liver cancer." (PMID 33372599, 2020). "Overall, RRM2 is a potential target for ferroptosis-based therapy to treat liver cancer." (PMID 33372599, 2020). "Since HepG2 and SMMC-7721 cells were shown to exhibit high carcinogenic properties in our previous studies and had the highest levels of RRM2 among the liver cancer cell lines tested, we thereby chose these two liver cancer cell lines as the main materials in subsequent experiments." (PMID 33372599, 2020). "Compared with AFP (positive likelihood ratio: 0.206 and negative likelihood ratio: 0.985), both RRM1 and RRM2 had greater positive likelihood ratios and less negative likelihood ratios, suggested that they might have a great diagnostic value for liver cancer." (PMID 36713030, 2023). "Therefore, HBV-related liver cancer was selected to verify the biological function of RRM2." (PMID 36518297, 2022). "Moreover, as demonstrated by CCK-8 and Edu assays, RRM2 was an oncogene in liver cancer cells." (PMID 36518297, 2022). "Subsequently, we evaluated whether RRM2 suppresses ferroptosis in liver cancer cells." (PMID 33372599, 2020). "Additionally, the potential usage of serum RRM2 as a biomarker to diagnose liver cancer remains unclear." (PMID 33372599, 2020). "Therefore, we investigated whether RRM2 acts as a potential target to suppress ferroptosis in liver cancer cells." (PMID 33372599, 2020). "Additionally, higher RRM2 expression in liver cancer signifies poorer overall survival." (PMID 33372599, 2020). "Ribonucleotide reductase regulatory subunit M2 (RRM2), a gene exhibiting increased expression in liver cancer, holds significant relevance in the field." (PMID 39118438, 2024). "Using the GeneMANIA database, we also identified RRM1-, RRM2-, and RRM2B-related molecules, which were also involved with liver cancer." (PMID 36713030, 2023). "Time-dependent ROC curves were adopted to compare the prognostic accuracy of RRM1, RRM2, and RRM2B in predicting the prognosis of liver cancer." (PMID 36713030, 2023). "To assess the potential impact of the RR subunits on chemotherapy of liver cancer, we evaluated the correlations between the expression levels of RRM1, RRM2, and RRM2B and multiple drugs." (PMID 36713030, 2023). "The ROC curve analysis demonstrated that the discriminative abilities of liver cancer for RRM1, RRM2, and RRM2B were 0.903 (95% CI: 0.873-0.933), 0.961 (95% CI: 0.939-0.984) and 0.767 (95% CI: 0.715-0.820), respectively." (PMID 36713030, 2023). "The expressions of RRM1, RRM2, and RRM2B were remarkably upregulated among liver cancer tissue both in mRNA and protein levels." (PMID 36713030, 2023). "DNA topoisomerase II alpha (TOP2A) and ribonucleotide reductase regulatory subunit M2 (RRM2) were discovered to be the most significant in PPI network analysis and survival analysis in liver cancer and for PCa." (PMID 35409038, 2022). "Further, ChIP–PCR experiments demonstrated that MYBL2 was physically recruited to the RRM2 promoter on the site 2 in CRC cells, similar to the ChIP-Seq data of MYBL2 in the liver cancer HepG2 cells." (PMID 34234118, 2021). "Subsequent validation suggested TOP2A, RRM2, NEK2, CDK1, and CCNB1 as the prognostic biomarkers of liver cancer." (PMID 34681056, 2021). "Our results suggest the potential use of TOP2A, RRM2, NEK2, CDK1, and CCNB1 as prognostic biomarkers in liver cancer." (PMID 34681056, 2021).
liver cancer (continued). "RRM2 antagonizes sorafenib, an FDA-approved multikinase inhibitor, to treat liver cancer, possibly due to its function to partially rescue liver cancer cells from sorafenib-induced long-term cytotoxicity." (PMID 33372599, 2020). "Next, we found RRM2, TK1, and TYMS to be strongly and significantly induced by about ten-, six- and fourfold, respectively, in liver cancer patient datasets from TCGA." (PMID 32587247, 2020). "AUC-ROC analysis also indicated that the combination of RRM2 with AFP to diagnose liver cancer (AUC: 0.947, 95% CI 0.919–0.974) was even better than either AFP or RRM2 alone, with a sensitivity of 88.7% and a specificity of 97.0%." (PMID 33372599, 2020). "In summary, their regulation, their association with survival, and their correlation of expression links lincNMR, YBX1, RRM2, TK1, and TYMS to liver cancer and to each other, respectively." (PMID 32587247, 2020). "Indeed, RRM2 and TK1 were decreased by YBX1 inactivation, which is involved in nucleotide metabolism in liver cancer cells." (PMID 40812419, 2025). "These genes, including RRM2, CCNB1, EZH2, and HMMR, are intricately involved in regulating essential cellular pathways and signaling cascades that are critical in the pathogenesis of liver cancer." (PMID 39118438, 2024). "In TCGA cohort, the expression of RRM1, RRM2, and RRM2B was significantly higher in liver cancer." (PMID 36713030, 2023). "According to recent reports, RRM2 could antagonize ferroptosis in liver cancer cells by sustaining glutathione (GSH) synthesis, which is a promising biomarker for the diagnosis of liver cancer." (PMID 35938001, 2022). "Ribonucleotide reductase regulatory subunit M2 (RRM2) is elevated in liver cancer tissues and cells, which could protect against ferroptosis of liver cancer cells." (PMID 34917129, 2021). "The lincNMR expression level significantly positively correlated with RRM2, TK1, and TYMS mRNA levels in HCC patient samples, further corroborating the strong link between lincNMR, these three regulators of nucleotide metabolism, and liver cancer." (PMID 32587247, 2020). "In addition, higher levels of RRM2 were detected in liver cancer cell lines (SK-Hep-1, Huh-7, Bel-7404, Bel-7402, SMMC-7721, HepG2) than in the hepatocyte line HL-7702, suggesting the potential role of RRM2 in promoting liver tumorigenesis." (PMID 33372599, 2020). "The mRNA levels of both Rrm2 and Prkd1 were higher in A/J than in A/J-12SM mice, but occurrence of liver cancer in A/J mice has not been reported." (PMID 27266874, 2016). "The results revealed DNA topoisomerase II alpha (TOP2A), ribonucleotide reductase regulatory subunit M2 (RRM2), never in mitosis-related kinase 2 (NEK2), cyclin-dependent kinase 1 (CDK1), and cyclin B1 (CCNB1) as the hub genes for liver cancer." (PMID 34681056, 2021). "However, whether and how RRM2 protects liver cancer cells against ferroptosis is still not known." (PMID 33372599, 2020).